MTOR (mechanistic target of rapamycin kinase)
Diseases named in the same sentence as MTOR in open-access papers (continued):
Sharing a sentence is not in itself a finding about the gene and the disease.
pancreatic cancer (continued). "Further preclinical studies and possible systematic trials are needed to evaluate the efficacy of combined MEK and mTOR inhibition as has been shown for pancreatic cancer and understand the mechanism." (PMID 37154160, 2023). "In obese/pre-diabetes mice induced by diet, metformin reduced pancreatic tumor growth and mammalian target of rapamycin (mTOR) related signal transduction (mTOR is a crucial complex involved in protein translation regulation)." (PMID 36829129, 2023). "In pancreatic cancer stem cells, Jade-1 has been implicated in the EMT phenotype through the AKT/mTOR pathway." (PMID 37175531, 2023). "Periplocin increased autophagy in pancreatic cancer cells by activating the AMPK/mTOR signaling pathway, as determined by measuring the protein expression levels of significant signaling pathways." (PMID 35847371, 2022). "Taken together, these data suggest that LL-37 decreased the autophagy levels in pancreatic cancer cells involved the activation of the mTOR pathway." (PMID 35935871, 2022). "SLC7A6 has also been shown in murine models to regulate glutamine-dependent mTOR activation and decrease sensitivity in pancreatic cancer, leading to the hopes of using it as a therapeutic target for pancreatic cells." (PMID 35967756, 2022). "The wound-healing assay showed that mTOR activation by MHY-1485 promotes the wound healing ability of pancreatic cancer." (PMID 35449152, 2022). "PI3K/Akt/mTOR and autophagy Signaling Pathway is frequently activated in pancreatic cancer and confers the tolerance to nutrition starvation within tumor microenvironment {reference}." (PMID 36235333, 2022). "Collectively, these results have shown that Periplocin promotes autophagy in human pancreatic cancer cells by regulating the AMPK/mTOR pathway." (PMID 35847371, 2022). "Macropinocytosis enables pancreatic cancer cells with activated KRAS and deficient PTEN to overcome mTOR inhibitor resistance." (PMID 35177645, 2022). "Conversely, LAT2 expression was associated with poorer survival in pancreatic cancer and was indicated to play a role in the pathogenesis of glomerulonephritis, both through LAT2-mediated mTOR activation." (PMID 36438828, 2022). "In pancreatic cancer, ALKBH5-mediated upregulation of DDIT4-AS1 maintains pancreatic cancer stemness and inhibits chemosensitivity through activation of the mTOR pathway." (PMID 36389678, 2022). "For example, quercetin can inhibit the expression of the receptor for advanced glycation end products (RAGE), inhibit the PI3K/AKT/mTOR axis, regulate the death of pancreatic cancer cells, and increase the chemosensitivity of gemcitabine." (PMID 35449823, 2022). "The second proposed mechanism was that the PI3K/Akt/mammalian target of rapamycin (mTOR) signaling pathway is involved in all of the signal regulation that is related to the survival and chemoresistance of pancreatic cancer cells." (PMID 36686732, 2022). "In particular, four of the eight candidate compounds in pancreatic cancer were MTOR-targeting drugs and were significantly more effective in EIF3C mutated cell lines than WT cell lines." (PMID 36517508, 2022). "Taken together, our findings suggest a supportive mechanism of the HGF/c-Met signaling pathway in promoting PNI by activating the mTOR/NGF axis in pancreatic cancer." (PMID 35449152, 2022). "An OA derivate namely CDDO-Me was found to inhibit PI3K/AKT/MTOR signaling in pancreatic cancer cells." (PMID 35482141, 2022). "At present, the drugs targeting pancreatic cancer stem cells mainly include Reactive oxygen species (ROS) inhibitors, acetylsalicylic acid, mTOR inhibitors, metformin, etc." (PMID 36505775, 2022). "In the present study, we first demonstrated that LL-37-induced autophagy suppression through mTOR activation leads to mitochondrial membrane potential decline and ROS accumulation as well as the resulting DNA damage in pancreatic cancer cells." (PMID 35935871, 2022).
pancreatic cancer (continued). "Canagliflozin showed these antiproliferative and apoptosis-inducing effects via the mTOR signalling pathway in pancreatic cancer cells." (PMID 36497303, 2022). "It was confirmed that canagliflozin exerted its antiproliferative and apoptosis-inducing effects via the mTOR signalling pathway on pancreatic cancer cells as well." (PMID 36497303, 2022). "Tet downregulates this signaling pathway and inhibits proliferation and invasion of glioma U87 cells, and also promotes PI3K/Akt/mTOR signaling pathway-mediated cell apoptosis and exert anti-gemcitabine-resistant pancreatic cancer effects." (PMID 36052124, 2022). "For example, miR-135b silencing inactivates the AKT/mTOR pathway and ultimately results in the inhibition of self-renewal and tumour growth of pancreatic cancer stem cells." (PMID 36056355, 2022). "We revealed that mTOR is required for the HGF/c-Met signaling pathway to exert its promoting effects on PNI in pancreatic cancer." (PMID 35449152, 2022). "The PI3K/Akt/mTOR signaling pathway is the most often activated in many cancer types, including pancreatic cancer, and regulates cancer cell survival, proliferation, metabolism, metastasis, and cancer invasion." (PMID 36235333, 2022). "Through a genome-wide CRISPR knockout library screen in pancreatic cancer cells treated with chemotherapeutic agents, we have identified the mTOR pathway as a prominent determinant of chemosensitivity." (PMID 36396656, 2022). "In the present study, we revealed that mTOR can regulate NGF expression as an upstream regulator in pancreatic cancer." (PMID 35449152, 2022). "RSL-3 can block the mTOR activation to promote GPX4 protein degradation in pancreatic cancer cells, which facilitates the autophagy-dependent ferroptosis induced by RSL-3." (PMID 36570007, 2022). "Mechanistically, HGF/c-Met signaling pathway can active the mTOR/NGF axis to promote the PNI of pancreatic cancer." (PMID 35449152, 2022). "Transfer of this miRNA in exosomes to sensitive cells activates the mammalian target of rapamycin (mTOR) signaling pathway conferring resistance to gemcitabine-sensitive pancreatic cancer cells." (PMID 35646668, 2022). "It was demonstrated that irisin can activate the AMPK pathway and downregulates the mTOR pathway, thereby suppressing pancreatic cancer cell growth." (PMID 36386179, 2022). "The data also indicate that in addition to regulating mTOR signaling in response to hypoxia, nutrient deprivation, and ER stress, REDD1 also controls mTOR activity in pancreatic cancers." (PMID 38089448, 2022). "Further study indicates that LL-37 suppressed autophagy in pancreatic cancer cells through activation of mTOR signaling, leading to more accumulation of ROS production and induction of mitochondrial dysfunctions." (PMID 35935871, 2022). "Actually, the important contribution of ERK1/2 signaling in MTOR activation and consequent autophagy inhibition has been widely described in pancreatic cancer cells." (PMID 34638477, 2021). "We demonstrated that the upregulation of mTOR enhanced cell viability and favored the Warburg effect in pancreatic cancer cells via the regulation of PI3K/AKT/mTOR signaling." (PMID 33849427, 2021). "Studies have revealed that mTOR was activated in pancreatic cancer tissues, and mTOR inhibitors are currently applied in molecular-targeted cancer therapies in clinical treatment." (PMID 33849427, 2021). "This latter study indicated that the mTOR signaling pathway participated in sestrin 2-mediated promotion and development of pancreatic cancer." (PMID 34784907, 2021). "Tan-IIA can block the Ras/Raf/MEK/ERK and PI3K/Akt/mTOR pathways, thereby inhibiting the malignant growth of human pancreatic cancer cells." (PMID 34588580, 2021). "Previously, we have shown that targeted inhibition of PI3K/Akt/mTOR together led to a significant reduction of tumor burden and improvement of overall survival in an aggressive mouse model of pancreatic cancer." (PMID 34503244, 2021).
pancreatic cancer (continued). "Our results suggested that fisetin inhibited proliferation, infiltration along with migration and triggered pancreatic cancer cells apoptosis through targeting the PI3K/AKT/mTOR cascade." (PMID 34821587, 2021). "Many signaling pathways, such as AMPK and mTOR signaling pathways, play an essential role in the progression of pancreatic cancer cells." (PMID 33231372, 2021). "PI3K-Akt-mTOR signaling cascade is frequently dysregulated and overactivated in pancreatic cancer, serving as an important etiology of the disease." (PMID 34620839, 2021). "In conclusion, KLK8 overexpression exerts pro-proliferation and anti-apoptotic functions in pancreatic cancer cells via EGF signaling-dependent activation of PI3K/Akt/mTOR pathway." (PMID 34395235, 2021). "In pancreatic cancer, the positive regulation of mTOR signaling hypophosphorylates 4E-BPs and activates S6 kinases, which leads to the initiation of translation process." (PMID 34944630, 2021). "It has been shown that downregulation of mTOR and P70S6K phosphorylation is associated with the inhibition of pancreatic tumor proliferation and metastasis, which is in agreement with the results shown in our study through the use of GEM and/or Evr." (PMID 33849427, 2021). "The results revealed that the AKT/mTOR signaling pathway is crucial for CSE1L-mediated pancreatic cancer proliferation." (PMID 33854580, 2021). "Previous studies have demonstrated that activation of PI3K/AKT/mTOR signaling pathway facilitates pancreatic cancer cell proliferation." (PMID 34395235, 2021). "Recent studies show that particular subtypes of pancreatic tumours respond well to anticancer agents that target the mTOR signalling pathway." (PMID 34506537, 2021). "In summary, our findings indicate that KLK8 overexpression exerts pro-proliferation and anti-apoptotic functions in pancreatic cancer cells via EGF signaling-dependent activation of PI3K/Akt/mTOR pathway." (PMID 34395235, 2021). "We also revealed that periplocin induces pancreatic cancer cell apoptosis through the AMPK/mTOR/S6K pathway." (PMID 33231372, 2021). "The PI3K/mTOR kinase inhibitor BEZ235 led to a rapid feedback activation of p-ERK in pancreatic cancer cells." (PMID 34037092, 2021). "Mechanistically, blocking the mTOR/p70S6K signaling pathway induced by TEOA leads to ACD in human pancreatic cancer cells." (PMID 34692691, 2021). "miR-99a-5p affects pancreatic cancer cell migration and invasion by regulating the mammalian target of rapamycin (mTOR)." (PMID 34680585, 2021). "Several oncogenes and tumor suppressors have been shown to modulate metabolic reprogramming in pancreatic cancer including PI3K/Akt/mTOR pathways." (PMID 34944630, 2021). "In pancreatic cancer cells, Akt-mTOR activation was largely inhibited by PCK1 shRNA, but was augmented after ectopic PCK1 overexpression." (PMID 34620839, 2021). "Our previous research has revealed that exosomal miR-210 derived from GEM-resistant pancreatic cancer cells mediated the horizontal transfer of drug-resistant traits via mTOR signaling." (PMID 33968986, 2021). "Palbociclib was also shown to work in synergy with multiple PI3K/mTOR inhibitors in pancreatic cancer cell lines." (PMID 34201419, 2021). "We demonstrated that Evr exhibited anti-cancer properties by inhibiting the activation of the PI3K/AKT/mTOR pathway to regulate glucose metabolism, tube formation, cell migration, and apoptosis in pancreatic cancer cells." (PMID 33849427, 2021). "Studies have shown that SSd can inhibit the activation of PSCs by activating PI3K/Akt/mTOR pathway and reduce the autophagy of PSCs, thereby improving pancreatic cancer fibrosis." (PMID 34714484, 2021). "To clarify the molecular mechanisms underlying the involvement of PKCε in the autophagic process, we focused our attention on MTOR, which is considered the main negative regulator of autophagy also in pancreatic cancer cells." (PMID 34638477, 2021).
pancreatic cancer (continued). "KLK8 overexpression also led to significant increases in phosphorylated 4EBP1 and phosphorylated S6P-p70S6K, two of the most distinctive downstream targets of mTOR, in pancreatic cancer cell lines." (PMID 34395235, 2021). "Another major hallmark of pancreatic cancer is the presence of several activated oncogenic signaling pathways, including PI3K/Akt/mTOR, which promotes disease aggressiveness and therapeutic resistance." (PMID 34503244, 2021). "Poor efficacy of Trametinib and other MEK inhibitors in pancreatic cancer is caused by a reciprocal increase or maintenance in alternate signalling activity, such as the AKT/mTOR pathway activity." (PMID 34824367, 2021). "We observed repression of the key translation initiation proteins (peIF4E, peIF4B, peIF4G, and p-mTOR) in steviol-treated pancreatic cancer cells." (PMID 34944630, 2021). "MUC16 also has a similar role in metabolic reprogramming in pancreatic cancer through the mTOR (mammalian target of rapamycin) and c-MYC pathways." (PMID 34681277, 2021). "Cell proliferation and invasion results showed that mTOR inhibitors (GSK2126458) can inhibit the proliferation of pancreatic cancer cells." (PMID 34461940, 2021). "In the present study, GSEA analysis and western blot assay revealed that KLK8 overexpression resulted in the activation of PI3K/AKT/mTOR signaling pathway in pancreatic cancer cells." (PMID 34395235, 2021). "Our findings agree with a previous report showing that OXA treatment stimulated the proliferation in pancreatic cancer cells by inhibiting apoptosis through the Akt/mTOR signaling pathway." (PMID 34577105, 2021). "RNA-seq analyzing of differentially expressed genes (DEGs) in PCK1-silenced pancreatic cancer cells implied that DEGs were enriched in the PI3K-Akt-mTOR cascade." (PMID 34620839, 2021). "The safe and well-tolerated anti-diabetic drug metformin was shown to efficiently suppress mTOR activation in pancreatic cancer, as well as other cancers." (PMID 32707920, 2020). "SLC7A8 or LAT-2 is an L-type amino acid transporter-2 protein that binds and regulates mechanistic target of rapamycin kinase (mTOR) activation in pancreatic cancer." (PMID 32235589, 2020). "Taken together, Neu2 overexpression into pancreatic tumors generated in NOD/SCID mice led to reduction of tumor growth via modulation of mTOR/Hh axis thereby reducing stemness-like properties and inducing apoptosis." (PMID 32575925, 2020). "Our research also found that mTOR acts as a downstream molecule of Sestrin2, and the suppression of mTOR signaling inhibited the proliferation of pancreatic cancer cells." (PMID 33343350, 2020). "In order to further study the role of Sestrin2 and mTOR signaling in pancreatic cancer, we conducted Sestrin2 overexpression and mTOR pharmacological inhibition experiments." (PMID 33343350, 2020). "We have observed that l-leucine can promote the proliferation of pancreatic cancer cells and increase the expression of Sestrin2 and p-mTOR proteins." (PMID 33343350, 2020). "mTOR expression and subsequent mTOR signaling pathways have been upregulated after RT in human pancreatic cancer biopsies." (PMID 33317198, 2020). "Rottlerin: Rottlerin, a natural product sequestered from Mallotus philippinensis, repressed PI3K/mTOR signaling in human pancreatic cancer stem cells, and activated autophagy-mediated apoptotic cell death." (PMID 33228222, 2020). "The mTOR signaling pathway is abnormally activated in pancreatic cancer and is related to tumor glucose metabolism." (PMID 33343350, 2020). "Bergamottin, a compound identified in C. hystrix, induced apoptosis in human pancreas cancer cells PANC-1 by inhibiting the Akt/mTOR signaling pathway, leading to inhibition of cell survival, proliferation, and migration." (PMID 33353129, 2020). "On the other hand, miR-138-5p suppresses autophagy by directly targeting SIRT1 expression and inhibits mTOR dephosphorylation under serum starvation-induced autophagy in pancreatic cancer." (PMID 33042011, 2020).
pancreatic cancer (continued). "Activated AMPK is associated with gluconeogenesis, lipogenesis, protein synthesis, and angiogenesis, and physiologically inhibits mTOR signaling, which is a critical pathway with respect to the prognosis of pancreatic cancer." (PMID 32580502, 2020). "Drugs targeting the mTOR pathway that are currently under clinical investigation for the treatment of pancreatic cancer include sirolimus (rapamycin) and its analogue everolimus." (PMID 32707920, 2020). "show that in pancreatic cancer cells with oncogenic KRAS and PTEN loss, scavenging of extracellular protein provides resistance against mTOR inhibition." (PMID 32101748, 2020). "The solute carrier SLC7A8 is known to promote glycolysis and chemoresistance in pancreatic cancer in an mTOR-dependent manner." (PMID 32785098, 2020). "Further, it is well established that some pancreatic cancer subtypes respond well to drugs which inhibit the mTOR pathway." (PMID 31988390, 2020). "Recently, a β-hydroxybutyrate-induced reduction of the mTOR oncogenic signalling pathway including c-Myc and its target genes has been reported in pancreatic cancer cells." (PMID 31727967, 2019). "AMPK/mTOR pathway plays an important role in Zn-CuO NPs-induced inhibition of human pancreatic cancer cells." (PMID 31001120, 2019). "Similar results have been observed in vivo, where mTOR inhibition resulted in reduced tumor growth and delayed progression in murine models of pancreatic cancer." (PMID 30459936, 2018). "In this study, Mfn2 was discovered increasing the cell autophagy by the PI3K/Akt/mTOR signaling pathway in pancreatic cancer." (PMID 30046371, 2018). "We consider that Mfn2 induces pancreatic cancer cell autophagy by inhibiting the PI3K/AKT/mTOR signaling pathway." (PMID 30046371, 2018). "To identify the effects of mTOR on glycolysis in pancreatic cancer cells, we then detected ECAR and glycoPER in MIA PaCa-2 and PANC-1 cells with LAT2 OE that were treated with RAD001." (PMID 30419950, 2018). "In a very recent observation from our group, we also established that association of cytosolic Neu2 with membrane triggers Fas-mediated apoptosis by impairing PI3K-Akt/mTOR pathway in pancreatic cancer cells (in press)." (PMID 29500369, 2018). "Further investigation revealed that orexin-A treatment activates theAkt/mTOR signaling pathway to promote cell proliferation byinhibiting Bcl-2/caspase-9/c-myc-mediated apoptosis in pancreatic cancer cells." (PMID 30429828, 2018). "Of these, the most significant was a Phase II study of the oral mTOR inhibitor, everolimus, in combination with capecitabine achieved an OS of 8.9 months in patients that presented with advanced pancreatic cancer (94% MPC)." (PMID 29765563, 2018). "Because it has been previously reported that HHAT inhibition by RU-SKI 43 negatively affected Akt and mTOR pathways in pancreatic cancer cells, we also assessed the impact of RU-SKI 43 on Akt and mTOR pathways in SAS and eSAS cells." (PMID 30338036, 2018). "Previous studies have described that orexin-A treatment can regulate theAkt/mTOR pathway in malignant tumors or tissues, encouraging us to clarify the mechanism of orexin-A-regulated cell proliferation in pancreatic cancer cells." (PMID 30429828, 2018). "Our finding suggests that Mfn2 induces cell autophagy of pancreatic cancer through inhibiting the PI3K/Akt/mTOR signaling pathway." (PMID 30046371, 2018). "In this study, we first proposed that Mfn2 can increase cell autophagy by the PI3K/Akt/mTOR signaling pathway in pancreatic cancer." (PMID 30046371, 2018). "Meanwhile, Mfn2 also significantly inhibited the expression of p-PI3K, p-Akt, and p-mTOR proteins in pancreatic cancer cells." (PMID 30046371, 2018). "Preclinical studies in pancreatic cancer cell lines displayed diverse effects of mTOR inhibitors on cell cycle progression, autophagy, reduced inflammation and inhibition of epithelial-to-mesenchymal transition." (PMID 30459936, 2018).